FDX1 (ferredoxin 1)
Diseases named in the same sentence as FDX1 in open-access papers (continued):
Sharing a sentence is not in itself a finding about the gene and the disease.
tumor (continued). "In contrast to the general population, HCC patients have a much lower level of FDX1 expression, while the low expression of FDX1 suggests a poor prognosis, tumor cells acquire a survival advantage over healthy cells by resisting cuproptosis." (PMID 37476384, 2023). "This includes an examination of FDX1 expression, its biological functions, alterations in the tumor immune microenvironment, and its correlation with drug sensitivity in GBM." (PMID 38114959, 2023). "HRD correlation analysis revealed that FDX1 expression was significantly related to HRD in 14 tumor types." (PMID 36825202, 2023). "In this study, FDX1 expression was positively correlated with tumor cell quiescence and inflammation, and negatively correlated with tumor invasion via CancerSEA database analysis." (PMID 36173462, 2023). "As a result, we do not have specific and comprehensive data that demonstrates the benefit of modulator of FDX1 in surviving cancer models or halting tumor growth." (PMID 37193786, 2023). "For STAD, FDX1 was positively correlated with citrate_cycle, DNA_repair, DNA_replication, G2M_checkpoint and tumor_proliferation, while negatively correlated with angiogenesis, apoptosis and tumor_inflammation." (PMID 37193786, 2023). "We observed the correlation of the expression of these feature genes in tumor samples, and found that most of them showed significant positive correlation except FDX1." (PMID 37239416, 2023). "Following that, we investigated FDX1 coexpression networks using the LinkedOmics database, which validated its function in tumor tissue, and illustrated that possibility using KIRC." (PMID 37193786, 2023). "Through bioinformatics and clinical tissues verification, we found that FDX1 was low expressed in tumor tissues of KIRC." (PMID 36755576, 2023). "Recent evidences have shown that FDX1 is highly correlated with lipoylated proteins abundance in a variety of human tumor cells, and cell lines with high levels of lipoylated proteins are sensitive to copper-induced cell death." (PMID 36173462, 2023). "NK cells, macrophages, and B cells in infiltration of the tumor tissue from high FDX1 cases were significantly enhanced." (PMID 37361595, 2023). "Firstly, we only verified the difference expression of FDX1 in tumor tissues and adjacent tissues of KIRC through clinical samples, and lacked further clinical experiments to verify immune infiltration and TILs." (PMID 36755576, 2023). "The differential expression of FDX1 was verified in clinical tumor tissues by RT-qPCR and immunohistochemistry (IHC)." (PMID 36755576, 2023). "First, to investigate the differential expression of FDX1 in tumor and normal tissue, the FDX1 mRNA expression was obtained from TCGA database." (PMID 36825202, 2023). "Tumor microenvironment and immune cell infiltration levels were found to differ significantly between groups with high and low FDX1 expression levels." (PMID 37301546, 2023). "The expression of FDX1 was downregulated in these six tumor tissues compared with the adjacent tissues." (PMID 36755576, 2023). "Natural killer cells, macrophages, and B cells were significantly enhanced, and PD-1 expression was low in the high-FDX1 tumor tissues." (PMID 37361595, 2023). "The TIMER2.0 and GEPIA databases were used to study the relationship between FDX1 expression and tumor-infiltrating immune cells." (PMID 37193786, 2023). "The correlation between FDX1 expression and tumor environment based on the ESTIMATE analysis was further investigated." (PMID 36825202, 2023). "We also found FDX1 had a prominent positive correlation with tumor stemness, HRD, and TMB in LGG while had an opposite correlation in KIRC." (PMID 36825202, 2023). "In GSE36895 and GSE53757, the expression of FDX1 was also verified to be lower in tumor tissues than in normal renal tissues (p < .05)." (PMID 36755576, 2023). "We applied multi classic immune deconvolution algorithms to investigate the correlation between FDX1 expression and tumor immunity." (PMID 36766692, 2023).
tumor (continued). "The aim of this study was to evaluate the association between Ferredoxin 1 (FDX1) expression and the prognostic survival of tumor patients and predict the efficacy of immunotherapy response to antitumor drug sensitivity." (PMID 37298135, 2023). "In a previous analysis of our study, we found that the FDX1 high expression phenotype was associated with an activated immune phenotype in ccRCC, and previous reports have indicated that the activation of cell death could enhance the anti-tumor efficiency in tumors." (PMID 36766692, 2023). "Then, the result of FDX1 expression in tumor cell lines showed that it was highest expressed in the intestine, stomach, and hematopoietic and lymphoid and lowest expressed in pleura and upper aerodigestive tract based on the CCLE database." (PMID 36825202, 2023). "We also constructed FDX1-overexpressing ccRCC cell lines to verify the impact of tumor immunity and tumor malignancy." (PMID 36766692, 2023). "HepG2 cells with FDX1 expression are sensitive to Cu2+, and interference of FDX1 promoted proliferation and migration of tumor cells." (PMID 37361595, 2023). "Overall, cuproptosis and tumor immune microenvironment were together involved in improvement of survival in patients with HCC with a high expression of FDX1." (PMID 37361595, 2023). "FDX1 has the potential to serve as a biomarker for pan-cancer prognosis and immunology, as well as a novel target for tumor therapy." (PMID 37193786, 2023). "Previous studies suggested that FDX1 inhibits tumor invasion by regulating the expression of tumor suppressor P73." (PMID 36173462, 2023). "This study investigated FDX1 expression features, and correlations to prognosis, tumor stages, immune microenvironment, and cuproptosis from a pan-cancer perspective based on integrated bioinformatics." (PMID 36825202, 2023). "More interestingly, FDX1 functioned as a promising biomarker and therapeutic target for ccRCC patients by reshaping tumor immunity." (PMID 36766692, 2023). "The methylation level decreased with an increase in tumor grade, with WHO grade IV tumors demonstrating the lowest methylation level; low methylation of FDX1 was also associated with a short progression free interval." (PMID 37301546, 2023). "Recently, a pan-cancer analysis revealed that ferredoxin 1 (Fdx1) is a key cuproptosis-related gene responsible for tumor immunity and drug sensitivity." (PMID 37305383, 2023). "Results showed that FDX1 was abnormally expressed in multiple tumor types and demonstrated variability in various tumor stages." (PMID 36825202, 2023). "It suggested that the role of FDX1 in the tumor immune microenvironment depended on tumor types and thus resulting in different outcomes." (PMID 36825202, 2023). "FDX1 was an independent prognostic molecule by Nomogram, and low expressed in tumor tissues compared with adjacent tissues (p < 0.05)." (PMID 36755576, 2023). "The correlation between FDX1 expression and immune checkpoints (ICP), microsatellite instability (MSI), and tumor mutational burden (TMB) in human cancers was analyzed using R 4.1.0." (PMID 37193786, 2023). "Similar to TCGA-LGG and TCGA-GBM, FDX1 was highly expressed in WHO IV (GBM) compared with WHO II, III (LGG), suggesting that other factors were intervening for FDX1 to affect the survival of tumor patients." (PMID 36825202, 2023). "Combined with the results based on in silico analysis, in this section, we first verified the differential expression at the RNA and protein levels, which indicated that ccRCC tumor tissues had a significantly dysregulated FDX1 expression level." (PMID 36766692, 2023).
tumor (continued). "We also investigated the relationship between FDX1 expression and immune subtypes, molecular subtypes of various cancer types, immunobiomarkers in the tumor microenvironment (TME), and effective small molecule drugs." (PMID 37193786, 2023). "FDX1 was investigated for its role in the immune mechanism and immune response of the tumor microenvironment (TME) by examining its relationship to tumor mutational burden (TMB) and Microsatellite Instability (MSI)." (PMID 37193786, 2023). "In our work, we calculated the correlation between FDX1 expression and tumor immunity in ccRCC, and found that the FDX1low subgroup led to an immune hot phenotype, while immune impressive signatures were also high in this subtype." (PMID 36766692, 2023). "In summary, these results suggest that FDX1 plays an essential role in tumor immunity and development." (PMID 36210836, 2022). "Although our study provides useful indications that FDX1 is involved in tumorigenesis and regulation of the immune environment of tumor cells, it does have some limitations." (PMID 36061184, 2022). "We validated this finding by performing a qRT-PCR analysis of 27 pairs of tissues from patients and demonstrated a consistent decrease in FDX1 mRNA expression in tumour tissues." (PMID 36186457, 2022). "The results showed that the FDX1 gene was abnormally expressed in most tumor tissues compared to normal tissues." (PMID 36523779, 2022). "Then, the lower expression of FDX1 in tumor tissues was identified in external and our own databases." (PMID 36536785, 2022). "Our study reveals that FDX1 can serve as a potential therapeutic target and prognostic marker for various malignancies due to its vital role in tumorigenesis and tumor immunity." (PMID 36210836, 2022). "All of these results indicated that KIRC was the tumor with the greatest potential to apply FDX1-related cuproptosis for therapy." (PMID 36605188, 2022). "The external databases demonstrated that in the level of bulk-RNA seq or single-cell RNA seq, the FDX1 was downregulated in tumor tissues, metastasis tumor cells and ccRCC epithelial cells." (PMID 36536785, 2022). "Next, the expression level of FDX1 in different tumor and normal tissues was further evaluated through the GEPIA online database." (PMID 36523779, 2022). "Meanwhile, a large majority of cuproptosis-associated genes including FDX1, LIAS, DLD, DLAT, PDHA1, and GLS, were significantly associated with the tumor microenvironment (immune, stromal, and estimate scores) (p < 0.05)." (PMID 36105090, 2022). "A comparison of mRNA expression among groups of tumour stages demonstrated that the ccRCCs of stages 3 and 4 showed the lowest FDX1 expression." (PMID 36186457, 2022). "Survival, immune infiltration, single-cell FDX1 expression, FDX1-related tumor mutational burden (TMB), microsatellite instability (MSI), stemness, tumor immune dysfunction and exclusion (TIDE), and immunotherapy-related analyses were performed." (PMID 36605188, 2022). "As the master regulator of cuproptosis, FDX1 was experimentally determined as a tumor suppressor to inhibit the cell growth and invasion of ccRCC cells." (PMID 36611966, 2022). "The hazard ratios of FDX1 to ACC, HNSC, KIRC, and LGG were significant, with FDX1 having the highest risk in LGG, and being a tumor suppressor factor in KIRC." (PMID 36061184, 2022). "To further investigate the potential value of FDX1, we explored the correlation of FDX1 with the tumor microenvironment and immune cell infiltration." (PMID 35991547, 2022). "We applied ImageJ to quantify the expression of FDX1 and found that the FDX1 level was higher in adjacent kidney tissues than that in KIRC tumor tissues, consistent with our previous series analysis." (PMID 36605188, 2022).
tumor (continued). "According to the ssGSEA algorithm, the low expression of FDX1 was related to tumor proliferation signature and DNA replication pathway (P < 0.05)." (PMID 36105937, 2022). "To further identify the lower expression of FDX1 in tumor tissues in our database, we performed RT-PCR in cell lines and 38 paired ccRCC tissues." (PMID 36536785, 2022). "Immune-related cell infiltration is the main mechanism affecting the tumor microenvironment, so we further investigated the relationship between FDX1 expression and immune infiltration analysis in pan-cancer." (PMID 35991547, 2022). "The expression of the FDX1 protein was downregulated in tumor tissues when compared with normal tissues in the Human Protein Atlas (HPA) database." (PMID 36536785, 2022). "The results from IHC staining also demonstrated that FDX1 expression was negatively correlated with ccRCC tumor initiation and progression." (PMID 36611966, 2022). "FDX1 is a key gene that promotes copperoptosis, and its impact on tumor pathogenesis and tumor immune response is indistinct and needs further exploration." (PMID 36061184, 2022). "To further understand the relationship between the tumor environment and FDX1, we used current public single-cell RNA sequence data to depict the expression portrait of FDX1 across all available tumors." (PMID 36605188, 2022). "In this study, FDX1 expression was significantly positively correlated with immune scores and tumor immune cell infiltration in several human cancers." (PMID 36387247, 2022). "FDX1 expression is closely correlated with almost all immune-related genes and contributes to tumor development." (PMID 36210836, 2022). "We also generated the miR-21-5p/FDX1 axis and experimentally verified the tumor-suppressive role of FDX1 in ccRCC cells." (PMID 36611966, 2022). "To verify the FDX1 expression level and its relationship with tumor functional status at the single-cell level in different cancers, we used the CancerSEA database." (PMID 36210836, 2022). "According to the malignancy cell type annotation, immune cells in most tumors took the main responsibility for FDX1 expression if we divided cells into immune cells, tumor cells, stromal cells, and other cells." (PMID 36605188, 2022). "In the TCGA-KIRC dataset, some genes were found to be differentially altered in normal and tumor tissues, especially FDX1 and PDHA (P< 0.05)." (PMID 36212447, 2022). "Higher FDX1 expression strongly enhanced tumor infiltration of macrophages, eosinophils, and Th2 cells but reduced infiltration of pDCs, NK CD56 bright cells, and Treg cells." (PMID 36579333, 2022). "Excluding those cancers without corresponding normal samples, significant differences in FDX1 expression were found between tumor and normal tissues in 17 types of cancer." (PMID 36210836, 2022). "FDX1, the cuproptosis master regulator, was experimentally determined as a tumor suppressor in ccRCC cells by suppressing the cell growth and cell invasion of ACHN and OSRC-2 cells in a cuproptosis-dependent and -independent manner." (PMID 36611966, 2022). "Using the Gene Expression Profiling Interactive Analysis and Tumor Immune Estimation Resource databases, we investigated the relationship between FDX1 gene expression, the degree of immune cell infiltration, and the corresponding gene marker sets." (PMID 36225932, 2022). "Next, to clarify the relationship between FDX1 gene expression and immune cell infiltration in the tumor microenvironment, the TIMER2.0 platform were used to analyze different dimensions of immunity." (PMID 36523779, 2022). "FDX1 gene is a key gene that promotes copperoptosis, so the study of FDX1 is significant for tumorigenesis, progression, tumor prognosis, tumor treatment, and many other aspects in practice." (PMID 36061184, 2022).
tumor (continued). "Slides were associated with lower IHC scores in the T3-4 group, AJCC stage 3–4 group, and ISUP grade 1–4 groups (p < 0.05), consistent with TCGA data mining of FDX1 mRNA expression based on tumour stage and grade." (PMID 36186457, 2022). "In our own database, FDX1 was downregulated in renal cancer cell lines and paired tumor tissues at both of mRNA and protein levels." (PMID 36536785, 2022). "Among the 33 cancer types in TCGA, the expression level of FDX1 was significant lower only in KIRC when comparing tumor tissues to adjacent normal tissues." (PMID 36536785, 2022). "Collectively, the current results begin to help us understand the crucial role of FDX1 in tumor biology and provide a novel direction for the application of cuproptosis in future tumor target therapies." (PMID 36605188, 2022). "Subsequently, we detected the expression of these CRGs in tumor and normal samples and found that 6 genes, FDX1, LIAS, DLD, DLAT, PDHB and MTF1, were significantly downregulated in tumors, while 2 genes, GLS and CDKN2A, were significantly upregulated." (PMID 36246586, 2022). "We compared normal and tumour tissues in 10 tumours, and FDX1 protein level was defined as the most significant difference in KIRC (p = 3.588E–54)." (PMID 36186457, 2022). "The expression of FDX1 in tumor and adjacent normal kidney tissue sections of all patients was detected by immunohistochemistry." (PMID 36212447, 2022). "WB analysis showed that in 16 pairs of ccRCC tissues, FDX1 expression was significantly higher in tumor-adjacent tissues than in tumor tissues." (PMID 36105937, 2022). "The results, especially for LGG and TGCT, suggest that FDX1 modulates tumor immune responses by modulating immune checkpoint activity." (PMID 36061184, 2022). "The abundance of FDX1 and adipoacylated protein is highly correlated in various human tumours, and cell lines with high levels of fatty acylated protein are sensitive to cell death induced by copper." (PMID 36388161, 2022). "It was determined that the FDX1 expression had strong correlations with gender (p = 0.006), histological tumor grade (p < 0.001), and pathological tumor stage (p < 0.001)." (PMID 36292610, 2022). "This called for more practical testing, so in the Taizhou cohort, we performed qRT-PCR experiments on 127 tumor tissues and their corresponding normal samples to obtain the expression of genes (FDX1, LIAS, PDHB, and MTF1)." (PMID 36212447, 2022). "Overall, this study constructed the miR-21-5p/FDX1 axis in ccRCC and analyzed its potential impact on the tumor microenvironment, providing valuable insights to improve current ccRCC management." (PMID 36611966, 2022). "IHC was performed to determine the expression levels of the FDX1 protein in samples from four patients with pairs of paratumoural tissues and primary tumour tissues." (PMID 36186457, 2022). "Given that FDX1 was hardly reported in tumor therapy, we present here a comprehensive pan-cancer analysis of FDX1." (PMID 36605188, 2022). "In ccRCC primary tumor specimens, FDX1 mRNA expression was significantly (p < 0.001) lower than in normal tissue specimens." (PMID 36225932, 2022). "First, we conducted expression analysis of FDX1 although different organs and compared the expression difference of FDX1 between normal tissues and tumor tissues." (PMID 36226187, 2022). "The proportion of FDX1 expression in tumor specimens was determined using the Z-score criterion, and the ccRCC cohort was then classified into low- and high-expression groups based on FDX1 expression levels." (PMID 36225932, 2022). "Taken together, these experimental data suggest that FDX1 functions as a tumor suppressor to influence ccRCC development at least by silencing physiological cuproptosis and triggering STAT3 signaling." (PMID 36611966, 2022). "FDX1 expression was also highly correlated with the T stage, tumor grade, and CD4+ T cell infiltration in the collected ccRCC samples." (PMID 36611966, 2022).